ATP1A1 (ATPase Na+/K+ transporting subunit alpha 1)
Diseases named in the same sentence as ATP1A1 in open-access papers (continued):
Sharing a sentence is not in itself a finding about the gene and the disease.
diabetes mellitus (1 paper, 2024). A metabolic disorder characterized by abnormally high blood sugar levels due to diminished production of insulin or insulin resistance/desensitization. "Specifically, five genes—ATF4, ATP1A1, B2M, CYBA, and PRNP—emerged with the highest inference scores in the context of T2D and Diabetes Mellitus, suggesting that these genes play critical roles in the molecular mechanisms underlying these conditions." (PMID 39926598, 2024).
Duchenne muscular dystrophy (1 paper, 2018). Duchenne muscular dystrophy (DMD) is a neuromuscular disease characterized by rapidly progressive muscle weakness and wasting due to degeneration of skeletal, smooth and cardiac muscle. "ATP1A1 is increased which controls the exchange of sodium and potassium ions across the sarcolemma, a process perturbed in Duchenne muscular dystrophy." (PMID 30153853, 2018).
esophageal neoplasm (1 paper, 2016). "One is that the human studies were cross-sectional, and as such they cannot be used to definitely conclude a causal link between ATP1A1 expression and the risk and progression of esophageal neoplasm." (PMID 27845894, 2016).
familial hyperaldosteronism (1 paper, 2021). "Somatic mutations in four genes (KCNJ5, ATP1A1, ATP2B3 and CACNA1D) have been identified in nearly 60% of the sporadic APAs, while germline mutations in KCNJ5 and CACNA1H have been reported in different subtypes of familial hyperaldosteronism." (PMID 34829937, 2021).
gastrointestinal stromal tumor (1 paper, 2022). "Furthermore, the results revealed that two of the four central DEGs (ATP1A2, PLN, KCNMA1, and SCNN1B) of the PPI network were created in this module, thus suggesting that PLN and ATP1A1 may have a significant important role in gastrointestinal stromal tumors." (PMID 35655923, 2022).
gout (1 paper, 2025). A condition characterized by painful swelling of the joints, which is caused by deposition of urate crystals. "The coordinated alterations in L-thyroxine, ATP1A1, and TTR within the thyroid hormone synthesis pathway suggest hypothalamic–pituitary–thyroid axis involvement, which may influence metabolic and inflammatory processes in gout." (PMID 41511324, 2025).
hearing loss (1 paper, 2023). "In addition, sensorineural hearing loss found in this patient has not been previously reported in ATP1A1 associated phenotypes." (PMID 36738336, 2023).
intestinal infection (1 paper, 2023). "ATP1A1 has played an important role as a host factor in SARS-CoV-2 infection, and inhibition of ATP1A1 expression blocked fetal intestinal infection." (PMID 36835408, 2023).
ischemic stroke (1 paper, 2023). A stroke disorder caused by obstruction of blood flow to the brain, due to thrombotic (local blood clot formation) or embolic (due to a blood clot or other material traveling from another site) event. "In addition, the novel mechanism of ATP1A1 as a mediator of signal transduction and autophagy during ischemia-reperfusion provides new ideas for the intervention of ischemic stroke." (PMID 37654494, 2023).
leukemia (1 paper, 2013). A malignant (clonal) hematologic disorder, involving hematopoietic stem cells and characterized by the presence of primitive or atypical myeloid or lymphoid cells in the bone marrow and the blood. "It is intriguing to note that genes like MAGEA3 and ATP1A1, which indicated potential over expression in our study, are also over expressed in leukemia/lymphoma." (PMID 23343470, 2013).
Listeria infection (1 paper, 2025). "Listeria infection further led to the loss of Na+/K+-ATPase subunits ATP1A1 and ATP1B1, and loss of Afadin and Nectin-3, suggesting a disruption of junctional integrity and polarity upon cell invasion." (PMID 41510227, 2025).
metabolic dysfunction-associated steatohepatitis (1 paper, 2023). Metabolic dysfunction-associated steatohepatitis (MASH, formerly known as nonalcoholic steatohepatitis or NASH) is a type of fatty liver disease. "In metabolic dysfunction-associated steatohepatitis (MASH)-related HCC, cellular redox imbalance from metabolic disturbances leads to dysregulation of the α1-subunit of the Na/K-ATPase (ATP1A1) signalosome." (PMID 37830582, 2023).
myopia (1 paper, 2023). "In addition, there is disrupted potassium ion homeostasis in the ciliary muscle in negative lens-induced myopia, and that this may be related to changes in the expression and activity of Na+/K+-ATPase, which is encoded by the ATP1A1 gene." (PMID 38136787, 2023). "Specifically, they noted that there is decreased expression of ATP1A1 at both the mRNA and protein levels in the ciliary muscles with negative lens induced myopia, as well as reduced Na+/K+-ATPase activity." (PMID 38136787, 2023).
neuropathy (1 paper, 2023). A disorder affecting the nervous system that manifests with pain, tingling, numbness, and/or muscle weakness. "Phenotypically, clinical presentation is similar to the previous cases reported, although the severity of the neuropathy, in this case, was more pronounced compared to other patients of comparable age group with ATP1A1 variants (CMTNSv2 12–15 in 40–50-year-olds)." (PMID 36738336, 2023).
Obesity (1 paper, 2025). Accumulation of substantial excess body fat. "Furthermore, obesity led to the up-regulation of sodium transporters (Slc13a1, Slc22a8, Slc17a1, Slc17a3) and the down-regulation of structural proteins (Col4a3, Col4a4) as well as Na/K-ATPase subunits encoded by Atp1a1, Atp1b1, suggesting impaired sodium metabolism and underlying renal injury." (PMID 41133844, 2025).
pancreatic cancer (1 paper, 2024). "It is interesting that higher gene expression of ATP1A1, which encodes the Na+/K+-ATPase that we showed regulating Na+-induced T cell activation, was also found to positively correlate with survival of patients with pancreatic cancer." (PMID 39198632, 2024).
pancreatic ductal adenocarcinoma (1 paper, 2022). An infiltrating adenocarcinoma that arises from the epithelial cells of the pancreas. "Inhibiting ATP1A1 expression in pancreatic ductal adenocarcinoma (PDAC) cells can suppress the tumor invasion." (PMID 36189312, 2022).
rectal cancer (1 paper, 2024). A primary or metastatic malignant neoplasm that affects the rectum. "Knockdown of the Na+/K+ ATPase subunit (ATP1A1) inhibits cell proliferation, migration, and invasion and induces apoptosis in rectal cancer cell lines HT29 and Caco2, suggesting that ATP1A1 regulates tumor progression through the ERK5 signaling pathway." (PMID 39703405, 2024).
rhabdomyosarcoma (1 paper, 2018). A rare aggressive malignant mesenchymal neoplasm arising from skeletal muscle. "In fact, ATP1A1 and GLG1 were previously shown to be upregulated after ectopic expression of EWSR1-FLI1 in the rhabdomyosarcoma cell line RD." (PMID 29416716, 2018).
viral hemorrhagic fever (1 paper, 2018). A viral infectious disease caused by RNA viruses in the Arenaviridae, Bunyaviridae, Filoviridae, or Flaviviridae family, and characterized by a severe multisystem syndrome, with damage to the vascular system and hemorrhaging. "Inhibitors of ATP1A1 (cardiac glycosides already used clinically for treatment of other diseases) suppressed multiplication in cell culture of Lassa virus and Junín virus, the two most significant viral hemorrhagic fever-causing mammarenaviruses." (PMID 29462184, 2018). "We next asked whether the ATP1A1 and PHB host-cell factors contributed also to multiplication of viral hemorrhagic fever-causing LASV." (PMID 29462184, 2018).
cancer (39 papers, 2010 to 2026). A tumor composed of atypical neoplastic, often pleomorphic cells that invade other tissues. "ATP1A1, a core gene, was associated with metabolic reprogramming and chemotherapy sensitivity across multiple cancers." (PMID 40821775, 2025). "Elevated ATP1A1 levels have been associated with advanced cancer staging, reduced recurrence-free survival (RFS), and overall survival (OS) in gastric cancer and hepatocellular carcinoma." (PMID 38178183, 2024). "Immune analyses showed that ATP1A1 expression was associated with heterogeneous immunomodulatory patterns, differences in immune cell infiltration, and reduced activity across several steps of the cancer immunity cycle." (PMID 42255487, 2026). "Our study focuses on ATP1A1, a sodium pump subunit associated with cancer development." (PMID 38178183, 2024). "In addition, the downregulation of the ATP1A1 gene, which encodes a catalytic α subunit of Na+/K+ ATPase, confers a significant sensitivity of cancer cells to aurilide B." (PMID 35956762, 2022). "In agreement with similar findings on different markers in other cancer entities, ATP1A1 and GLG1 may have diagnostic as well as prognostic utility." (PMID 29416716, 2018). "Dysregulated ATP1A1 expression has been reported in multiple cancers, including breast 29, gastric 30, colon 31, and non-small cell lung cancer (NSCLC) 32, where its suppression inhibits cell proliferation 30,31 and migration." (PMID 41362742, 2026). "Yet, the functional significance of endosomal/lysosomal ATP1A1 and its potential contribution to cancer progression, particularly in the context of drug resistance, remains largely unexplored." (PMID 41362742, 2026). "RNA sequencing data from the TCGA database to assess the expression of ATP1A1 across multiple cancer types using the TCGAplot R package." (PMID 40821775, 2025). "ATP1A1 expression showed a positive correlation with sensitivity to several chemotherapy drugs in pan-cancer." (PMID 40821775, 2025). "In the pan-cancer analysis of ATP1A1, we also discovered the heterogeneity of ATP1A1, showing completely opposite effects in different tumor types." (PMID 40821775, 2025). "Molecular docking and pan-cancer analyses were conducted to identify therapeutic candidates and ATP1A1-related mechanisms." (PMID 40821775, 2025). "This evidence supports that ATP1A1 has potential as a prognostic marker and a therapeutic target in various types of cancer." (PMID 38730618, 2024). "The multifactorial marker ATP1A1/BCL2L1 improves the prediction of the response of cancer cells to CGs." (PMID 37904054, 2024). "AML was within the top three and the ninth highest ATP1A1/BCL2L1 expressing types of cancer, respectively, across 40 cancer cell lineages (Cancer Cell Line Encyclopedia, CCLE, portal and 33 tumor types (TCGA pan-cancer cohort)." (PMID 37904054, 2024). "Studies on the clinical significance of ATP1A1 expression have also been reported in other cancer models." (PMID 38730618, 2024). "It must be noted that silencing or inhibiting the expression of ATP1A1 can inhibit the proliferation and migration ability of cancer cells." (PMID 36985801, 2023). "A decrease in ATP1A1 expression has also been observed in several human cancers such as prostate, kidney and bladder, which lead to accelerated proliferation." (PMID 35982918, 2022). "Further investigations of the remaining genes such as FN1, EEF1A1, COL1A1, SFTPB, SFTPC, and ATP1A1 will shed light on the identification of novel biomarker genes for a pan-cancer cohort." (PMID 31324856, 2019). "Aberrant expression of Na+/K+-ATPase α1 subunit (ATP1A1) is widely observed in multiple types of tumors, and its tissue-specific expression relates to cancer development." (PMID 28484360, 2017). "ATP1A1 was 12.3 times (adjusted odds ratio=12.3, 95% CI = 7.2-21.0) more likely to be overexpressed in cancer tissues than in normal tissues." (PMID 27845894, 2016).
cancer (continued). "The future studies should collect a series of measurements of ATP1A1 in patients before and after cancer treatment to further confirm the role of ATP1A1 as a tumor marker." (PMID 27845894, 2016). "Categorizing samples into those with IHC score of < 1 and ≥ 1, we found that the significantly higher frequency of ATP1A1 overexpression in cancer tissues than in normal ones after adjusting for age and sex (AOR = 12.3, 95% CI = 7.2-21.0)." (PMID 27845894, 2016). "Additionally, pan-cancer analyses revealed ATP1A1’s involvement in metabolic regulation, therapeutic target, and immune cell infiltration, offering mechanistic insights into KIRC pathogenesis." (PMID 40821775, 2025). "Finally, to assess the potential clinical relevance of ATP1A1, univariate Cox regression analysis identified ATP1A1 as a significant prognostic factor for OS in cancer patients." (PMID 40821775, 2025). "Additionally, we examined the methylation patterns of ATP1A1 across different cancer types and genetic loci." (PMID 40821775, 2025). "Furthermore, to demonstrate that bufalin acts as an anti-cancer agent specifically when ATP1A1 is located in caveolae, we used methyl-β-cyclodextrin (MBCD) to disrupt caveolae formation." (PMID 38178183, 2024). "In contrast, normalization of the ATP1A1 signaling significantly decreased H3K9ac and H3K9me3, in vitro and in vivo, with concomitant nuclear localization of FoxO1, heightening cell autophagy and cancer-cell apoptotic activities in treated HCC cell lines." (PMID 37830582, 2023). "In addition, ATP1A1 has been found to be overexpressed in a variety of cancer cells, such as breast cancer, liver cancer and glioma." (PMID 36835408, 2023). "To gain further mechanistic insight, we explored potential signalling pathways that could mediate the effects of cardiac glycosides and ATP1A1 knockdown on immune checkpoint protein expression in TNF/IFN-ɣ-stimulated cancer cells." (PMID 35150740, 2022). "We hypothesized that the level of ATP1A1 expressed in this cancer cell line exceeds that of its obligate partner ATP1B1, and thus ATP1A1 is recognized by HSP70/HSC70 constitutively in these cells." (PMID 32687490, 2020). "Consistent with previous studies of other cancer cell lines, our in-vitro experiments showed that ATP1A1 expression is highly correlated with the invasive ability of a subpopulation from the same ESCC cell line (CE81T vs. CE81T-4) established in our laboratory." (PMID 27845894, 2016). "An association between germline mutations of four genes (FLT3, HOXD11, TCF3, and ATP1A1) and cancer has not been reported." (PMID 27701467, 2016). "In addition to exchanging cations, ATP1A1 is also involved in the tumorigenesis and migration of cancer cells." (PMID 27845894, 2016). "Aberrant expressions of both ATP1A1 a1 and ATP1A1 b1 have been reported in various cancers." (PMID 27845894, 2016). "Thus, downregulation of ATP1A1 expression in cancer cells is expected to affect several processes of cellular function." (PMID 26334094, 2015). "Similarly, inhibition of the Na+/K+ transporter ATPase ATP1A1 was recently shown to induce sensitization to anoikis in cancer cells." (PMID 21203533, 2010). "Indeed, the inhibition of ATP1A1 using CGs was reported to be an option for cancer therapy." (PMID 38730618, 2024). "The cancer cell modules (I) of the two samples are characterized by distinct marker genes, i.e., PMEL, ATP1A1, and SPP1 in sample 1 whereas S100B and PSAP in sample 2, in line with previous studies." (PMID 40033360, 2025). "To further validate our data, we tested the protein expression of the ATP1A gene family members (including ATP1A1, ATP1A2, and ATP1A3) in cancer and paracancerous tissue samples of six patients with OSC." (PMID 32684846, 2020). "Among the paired cancer and adjacent normal tissues from 14 ESCC patients, 10 pairs (71.4%) had overexpression of ATP1A1 (ATPase Na+/K+ transporting alpha 1 polypeptide) by qPCR (P = 0.0052)." (PMID 27845894, 2016).
cancer (continued). "Such analysis could shed light on whether LncDARS‐AS1‐mediated regulation of ATP1A1 and NKA activity might serve as a target in other cancer types, thereby offering a potential therapeutic avenue for a wider range of malignancies." (PMID 40665639, 2025). "ATP1A1, KMT2E and WASF2 were known as the hallmarker of cancers and overexpression of these genes promote the survival of cancer cells, while RAD23A acts as a negative regulator of anti-virus response and might correlate directly with the HPV infection." (PMID 36420261, 2022). "Although the ATP1A1 is greatly decreased even lost in RCC tissues, it is accurate to catch its downregulation by the sensitive quantitative proteomics identification, which provides a rapid approach to discover novel cancer biomarkers." (PMID 28484360, 2017). "In total, IHC staining found ATP1A1 to be expressed in 369 ESCC tissue specimens from three different countries (Taiwan, Korea, and USA), which included 126-paired samples with cancer parts and their normal parts and 243 cancer samples only." (PMID 27845894, 2016). "ATP1A1 expression was negatively correlated with the infiltration of regulatory T cells (Tregs), follicular helper T cells, CD8+ T cells, CD4+ T cells, and memory B cells across most TCGA cancers, while it showed a positive correlation with macrophage infiltration in various cancers." (PMID 40821775, 2025).